ADAMTS4 (ADAM metallopeptidase with thrombospondin type 1 motif 4)
Diseases named in the same sentence as ADAMTS4 in open-access papers (continued):
Sharing a sentence is not in itself a finding about the gene and the disease.
aneurysm (4 papers, 2020 to 2023). Bulging or ballooning in an area of an artery secondary to arterial wall weakening. "The ADAMTS4-specific probe enables the in vivo imaging-based prediction of aneurysm expansion and rupture." (PMID 35606349, 2022). "There is also accumulating evidence that the extracellular matrix enzyme ADAMTS4 is strongly upregulated in an aneurysm, and therefore represents a promising in vivo target to assess the risk of rupture." (PMID 35606349, 2022). "Here the authors report the development of an imaging probe for ADAMTS4, which they test in an abdominal aortic aneurysm mouse model and show in vivo prediction of aneurysm and rupture." (PMID 35606349, 2022). "An increased expression of ADAMTS4 may promote aneurysm progression by degrading ECM components and facilitating inflammatory cell infiltration." (PMID 35606349, 2022). "They showed that ADAMTS-4 deficiency resulted in reduced aneurysm and dissection formation, with associated maintenance of normal elastin fibre arrangements, reduced inflammatory cell infiltration and apoptosis, with reduced versican degradation." (PMID 36012466, 2022). "As our microarray results suggested that ADAMTS‐4 expression was negatively correlated to miR‐126a‐5p in aneurysms and control aortas in mice, we then investigated whether miR‐126a‐5p could down‐regulate ADAMTS‐4." (PMID 32469162, 2020). "In order to evaluate the localization of ADAMTS4, SMCs, and CD68 + cells within the aneurysm, immunofluorescence analysis of 10 μm thick AAA cryosections after 4 weeks of AngII-infusion was performed." (PMID 35606349, 2022). "The incomplete overlap is highly likely due to the fact that not all SMCs and macrophages in the aneurysm express ADAMTS4 simultaneously." (PMID 35606349, 2022).
chondrosarcoma (4 papers, 2015 to 2023). A malignant cartilaginous matrix-producing mesenchymal neoplasm arising from the bone and soft tissue. "Two other groups had similar findings when they applied ADAMTS-4 transfected human chondrosarcoma cells or IL-1 treated bovine cartilage tissues." (PMID 25909781, 2015). "ADAMTS-4 and ADAMTS-5 levels were increased by 83.7 and 82.5%, respectively, in IL-1β-treated human chondrosarcoma cell line SW1353." (PMID 33321982, 2020). "Compared with IL-1β-treated human chondrosarcoma cell line SW1353, ADAMTS-4 and ADAMTS-5 expression were decreased dose dependently in the 20 μg/mL CZE and 0.4 μg/mL linarin treatments." (PMID 33321982, 2020). "We first verified that transcriptional expression of MMP1, MMP3, MMP13, and ADAMTS4 was upregulated by IL-1β or TNF-α and repressed by I-BET151 in a human chondrosarcoma cell line (SW1353)." (PMID 30786900, 2019).
diabetes (4 papers, 2020 to 2026). "Recurrent hypoglycaemia in the absence of diabetes was associated with changes in a small subset of genes associated with endothelial integrity, β-adrenergic signalling and heart failure, including Cldn5, Akap12, Nr4a2 and Adamts4." (PMID 41212210, 2026). "In the present study, expression of AdamTS4 and Timp1 was up-regulated in regenerating bone fractures of wt and db−/db− generally, whereas up-regulation in bones of mice with diabetes was statistically not significantly higher than in wt bone." (PMID 35207422, 2022).
intervertebral disc degeneration (4 papers, 2012 to 2020). "In a static pressure-induced rat model with caudal intervertebral disc degeneration, the mRNA levels of ADAMTS4, ADAMTS5, ADAMTS7, and ADAMTS12 were found to be increased significantly." (PMID 32855969, 2020). "Meanwhile, ADAMTS4 is an autocrine factor of the nucleus pulposus cells and particularly crucial of degrading proteoglycans in intervertebral disc degeneration." (PMID 28512264, 2017). "Thus, inhibiting the release of ADAMTS4 is of great importance for intervertebral disc degeneration, because ADAMTS4 is an autocrine factor of the nucleus pulposus cells." (PMID 28512264, 2017). "In addition, after GA was added into the culture medium of intervertebral disc degeneration rat model, immunohistochemistry showed that GA had an inhibitory effect on the distribution of ADAMTS4 in rat nucleus pulposus cells." (PMID 28512264, 2017). "Thus, antagonizing or regulating the effect of inflammatory factors can affect ADAMTS4 secretion in the nucleus pulposus cells, thereby delaying intervertebral disc degeneration." (PMID 28512264, 2017). "ADAMTS-4 expression increased both in the TNF-α-induced nucleus pulposus cells and intervertebral disc degeneration rat model." (PMID 28512264, 2017). "A dominant imbalance of MMP-3/TIMP-1 and TIMP-2 relative to ADAMTS-4 and ADAMTS-5/TIMP-3 signifies an advanced stage of intervertebral disc degeneration." (PMID 22394620, 2012). "A dominant imbalance of MMP-3/TIMP-1 and TIMP-2 relative to ADAMTS-4 and ADAMTS-5/TIMP-3 is a possible indication of an advanced, irreversible stage of intervertebral disc degeneration." (PMID 22394620, 2012). "Integrated with these reports, our findings show that a state of dominant MMP-3/TIMP-1 and TIMP-2 imbalance relative to ADAMTS-4 and ADAMTS-5/TIMP-3 imbalance may indicate an irreversible stage of intervertebral disc degeneration." (PMID 22394620, 2012).
joint diseases (4 papers, 2013 to 2023). "Our results suggest that unlike ADAMTS-4 and ADAMTS-5, which are widely recognised as destructive aggrecanases in joint disease, the aggrecanolytic activity of ADAMTS-9 might be more important for normal joint development than for pathology." (PMID 30699963, 2019).
Stroke (4 papers, 2013 to 2024). Sudden impairment of blood flow to a part of the brain due to occlusion or rupture of an artery to the brain. "On one hand, it has been reported that ADAMTS4 negatively affects the integrity of the cerebral blood vessels, increasing the risk of hemorrhagic transformation and edema after stroke." (PMID 37378751, 2024). "Adamts4 is of interest since it for the first time is shown to be upregulated in the cerebral arteries in response to stroke." (PMID 33297959, 2020). "Surprisingly, it is only recently that the upregulation of ADAMTS-4 and -5 mRNA levels were detected in astrocytes after tMCAO in mice 24 hours after stroke onset." (PMID 24176075, 2013). "Adamts4 mRNA expression is upregulated in astrocytes following transient middle cerebral artery occlusion in the rat, but this is the first study reporting their modulation in regions remote from the lesion after permanent stroke." (PMID 28290150, 2018). "The aim of this study was to further investigate the influence of multisensory brain stimulation provided by EE after stroke on PNN integrity and on changes in expression/activity of MMP-2 and MMP-9, tPA, ADAMTS-4, and their inhibitors." (PMID 28290150, 2018). "Here, Adamts4 mRNA expression was statistically 45% higher in the stroke STD group compared to the sham STD group (P < 0.05 among our four experimental groups; sham STD vs stroke STD, P < 0.05)." (PMID 28290150, 2018). "In order to discern if the increased activity of MMP-9 and tPA that we see in the stroke EE group was due to changes in expression of respective ECM proteases, mRNA levels of Mmp9, as well as Adamts4, Tpa, and their inhibitors (respectively, Timp1, Timp3, and Neuroserpin) were studied by RT-qPCR." (PMID 28290150, 2018). "In the contralateral hemisphere, Adamts4 mRNA expression was upregulated after stroke, but not after stroke and EE conditions, a tendency also seen in Timp3 and Neuroserpin." (PMID 28290150, 2018). "Because TNF-α was shown to promote ADAMTS-1 and -4 mRNA levels as well as ADAMTS-4 and -5 protein levels in human astrocyte cultures, it was hypothesized that the increase of TNF-α expression in the acute phase of stroke may be responsible for the upregulation of ADAMTS-1 and -4 by astrocytes." (PMID 24176075, 2013).
aortic aneurysm (3 papers, 2022 to 2025). A ruptured aneurysm located in the wall of the proximal portion of the descending aorta proceeding from the arch of the aorta. "By using the ADAMTS4-specific probe, a significant increase of in vivo MR enhancement was observed in the wall of aortic aneurysms." (PMID 35606349, 2022). "ADAMTS4-MRI could improve the in vivo characterization of aortic aneurysms." (PMID 35606349, 2022).
colorectal cancer (3 papers, 2015 to 2022). A primary or metastatic malignant neoplasm that affects the colon or rectum. "ADAMTS4 was reported to promote tumor growth in colorectal cancer and is associated with macrophage infiltration." (PMID 31900160, 2020). "Further investigation of the copy number variation of ADAMTS8 did not support this epigenetic regulatory mechanism in colorectal cancer linked to ADAMTS4." (PMID 35743687, 2022). "Our findings support the notion that overexpression of ADAMTS-4 and ADAMTS-5 in colorectal cancer might be a possible invasive mechanism of cancer cells in order to degrade proteoglycans of ECM." (PMID 25786261, 2015).
heart failure (3 papers, 2014 to 2026). Inability of the heart to pump blood at an adequate rate to meet tissue metabolic requirements. "To summarize, the increased levels of ADAMTS4 seem to be consistent across different patient cohorts and models related to heart failure and cardiac fibrosis." (PMID 37216909, 2023). "Although fibrosis occurs in most forms of heart failure, the activity of ADAMTS4 in other phenotypes than those examined in our study should be clarified to further support the translational potential of these findings." (PMID 37216909, 2023). "Taken together, these data indicate that ADAMTS4 activity, including fibronectin cleavage, is increased in human heart failure." (PMID 37216909, 2023). "Targeting ADAMTS4 may serve as a novel strategy in heart failure treatment, in particular, in heart failure with fibrosis and diastolic dysfunction." (PMID 37216909, 2023). "We investigated whether the ECM enzyme known as A disintegrin and metalloprotease with thrombospondin motif (ADAMTS) 4 might serve as a therapeutic target in treatment of heart failure and cardiac fibrosis." (PMID 37216909, 2023). "The translational potential of ADAMTS4 as a therapeutic target is supported by the findings of the beneficial effects of ADAMTS4 inhibition in rat hearts following pressure overload and that substantially increased ADAMTS4 activity is observed in human heart failure." (PMID 37216909, 2023). "To determine whether myocardial ADAMTS4 activity is increased during human heart failure, we assessed the level of active ADAMTS4 protein and its cleavage products in explanted hearts with dilated cardiomyopathy (DCM) (see Supplementary materialonline)." (PMID 37216909, 2023). "Taken together, these findings indicate that ADAMTS4 is a central mediator of cardiac fibrosis, and therefore, it may be a target for the treatment of patients with cardiac fibrosis and heart failure (Graphical abstract)." (PMID 37216909, 2023). "Our findings suggest that AB induces an increase in myocardial ADAMTS4 versicanase activity, and that PPS-treatment improved systolic function in the pressure-overloaded heart, holding promise as a novel therapeutic agent in heart failure." (PMID 24595230, 2014). "Synthesis of ADAMTS4 and versican in cardiac cells was induced in vitro by TNF-α and IL-1β, cytokines found in enhanced levels in the failing myocardium, suggesting inflammation as a trigger for ADAMTS-mediated versican fragmentation in heart failure." (PMID 24595230, 2014). "Interestingly, ADAMTS4 synthesis in macrophages increases in response to tumor necrosis factor (TNF)-α and interleukin (IL)-1β, cytokines which are found increased in the myocardium of heart failure patients, suggesting a role in heart failure development." (PMID 24595230, 2014).
hepatocellular carcinoma (3 papers, 2019 to 2026). A malignant tumor that arises from hepatocytes. "This relatively large‐size retrospective study was conducted to investigate the association between ADAMTS4 single‐nucleotide polymorphisms and the risk and prognosis of hepatocellular carcinoma (HCC)." (PMID 31663692, 2019). "In addition to its role in the growth of early-stage lung cancer, ADAMTS4 promotes tumor progression in hepatocellular carcinoma, lung cancer, and CRC." (PMID 41358726, 2026). "ADAMTS4, the targeted mir-1268a gene, is affected by pre miRNA polymorphism to reveal the risk of AFB1 related hepatocellular carcinoma(HCC)." (PMID 35737034, 2022).
Hypertension (3 papers, 2020 to 2021). The presence of chronic increased pressure in the systemic arterial system. "Interestingly, ADAMTS-4 expression was increased in the myocardium of rats subjected to hypertension and addition of pentosan polysulfate inhibited both Adamts4 expression and versican cleavage and ameliorated myocardial function." (PMID 33352066, 2020).
influenza infection (3 papers, 2023 to 2026). "We previously reported that the ECM protease ADAMTS4 mediates lung injury during influenza infection." (PMID 41258714, 2026). "Furthermore, our previous study demonstrated that extracellular matrix (ECM) proteases, particularly ADAMTS4, play a key role in the immunopathogenesis of influenza infection by driving excessive lung inflammation and tissue damage." (PMID 40920865, 2025). "In cases of severe influenza infection, inflammatory lung fibroblasts may drive lethal immunopathology based on the activity of the ECM protease ADAMTS4, which is consistent in mouse models and severe human influenza infection." (PMID 37655660, 2023).
knee osteoarthritis (3 papers, 2019 to 2024). "However, Canbek et al36 reported that two SNPs (rs226794 and rs2830585) in the ADAMTS4 did not change knee osteoarthritis risk." (PMID 31663692, 2019).
tendinopathy (3 papers, 2008 to 2015). "Further studies will be required to determine the contribution of ADAMTS-4 to the observed changes in proteoglycans in tendinopathy." (PMID 18387286, 2008). "The current and previously identified decrease in ADAMTS4 may be a consequence of the acute nature of the tendinopathy and/or of particular importance for injury-induced pathology." (PMID 25837713, 2015). "The greater decrease in ADAMTS4 distant from the lesion, and increased VCAN predominantly proximal, suggest additional complex regulatory control of injury-induced tendinopathy." (PMID 25837713, 2015). "MMP2, MMP3, MMP8, ADAMTS2, ADAMTS4, ADAM12 and collagen type I expression were regulated in a similar manner in tendinopathy compared to the current study." (PMID 23830915, 2013).
acute coronary syndrome (2 papers, 2016 to 2023). Signs and symptoms related to acute ischemia of the myocardium secondary to coronary artery disease. "Recent reports indicated elevated ADAMTS4 level in human atherosclerotic plaques and in the plasma of acute coronary syndrome patients." (PMID 27491335, 2016). "In addition, some studies showed changes in plasma ADAMTS4 levels in other inflammatory diseases, such as acute coronary syndrome." (PMID 36721026, 2023). "In addition, elevated levels of ADAMTS4 were also observed in peripheral monocytes in human acute coronary syndrome patients." (PMID 27491335, 2016).
amyotrophic lateral sclerosis (2 papers, 2016 to 2021). Amyotrophic lateral sclerosis (ALS) is a neurodegenerative disease characterized by progressive muscular paralysis reflecting degeneration of motor neurons in the primary motor cortex, corticospinal tracts, brainstem and spinal cord. "Therefore, we investigated the expression, effects and associated mechanisms of ADAMTS-4 during amyotrophic lateral sclerosis (ALS) in the SOD1G93A mouse model." (PMID 26809777, 2016). "Furthermore, the effects of MMP-2 and ADAMTS-4 are additive in degrading brevican, which may offer one plausible explanation for the ability of exogenous ADAMTS-4 to degrade PNNs in amyotrophic lateral sclerosis model SOD1G93A mice in which PNN breakdown had already occurred, but not WT mice." (PMID 34413489, 2021).
colon cancer (2 papers, 2020 to 2023). "ADAMTS4 is highly expressed in colon cancer and is associated with poor prognosis." (PMID 32884571, 2020). "ADAMTS4 is highly expressed in colon cancer cells, and research suggested that ADAMTS4 can promote cancer progression through macrophages." (PMID 36755247, 2023).
dementia (2 papers, 2020 to 2021). Loss of intellectual abilities interfering with an individual's social and occupational functions. "We aimed to develop two assays capable of detecting the brevican N-terminal (N-Brev) and the ADAMTS4-generated fragment (Brev-A), cleaved at Ser401, in serum and to perform a preliminary assessment of their diagnostic potential in dementias." (PMID 32559242, 2020). "In relation to Alzheimer ́s disease and other dementias, it has been proposed that differential levels of brevican and the fragments generated after ADAMTS-4 proteolysis could be employed to distinguish among different types of dementias." (PMID 33804223, 2021).
fibrosis (2 papers, 2022 to 2024). the formation of excess fibrous connective tissue in an organ or tissue in a reparative or reactive process. "Specifically, we used mRNA expression of Krt8 (indicative of injury/repair), Krt5 (related to dysfunctional repair), Adamts4 (associated with fibrosis), and Itga5 (indicative of damage-responsive fibroblasts)." (PMID 39340037, 2024). "Finally, not only our marker of interest, Adamts4 but also α-SMA showed significantly enhanced expression in patients with MI and DCM injury indicating a cardiac fibrosis like condition following adult cardiac injury." (PMID 35701493, 2022).
gliosarcoma (2 papers, 2019 to 2020). A rare histological variant of glioblastoma (WHO grade IV) characterized by a biphasic tissue pattern with alternating areas displaying glial and mesenchymal differentiation (WHO). "More interestingly, we found several genes highly up-regulated in gliosarcoma, including the genes encoding proteins putatively related to differentiation: UNC5B, a metallopeptidase (ADAMTS4) and a collagen COL18A1, in comparison to GBMs (log2 fold change)." (PMID 30818875, 2019). "Active ADAMTS4 digests several ECM constituents including the brain-specific brevican, and enables brain invasion of 9L rat gliosarcoma cells." (PMID 32872536, 2020).
multiple sclerosis (2 papers, 2016 to 2024). A progressive autoimmune disorder affecting the central nervous system resulting in demyelination. "Adamts4 protein levels are elevated in the EAE model of multiple sclerosis and spinal cord injury." (PMID 39091874, 2024). "Modifications of ADAMTS-4 expression/activity have been reported during spinal cord injury (SCI), experimental autoimmune encephalomyelitis and multiple sclerosis." (PMID 26809777, 2016).
prostate carcinoma (2 papers, 2015 to 2024). A carcinoma that arises from epithelial cells of the prostate gland. "In this study, we identified several genes including the cytokines Il-6, Tgfb2, Cxcl1, and Ctgf, metallopeptidases Mmp13, Adamts1, Adamts4, and Adamts5, and transcription factors Junb, Fos, Stat3 and Cebpb that were up-regulated in osteoblasts as a result of prostate cancer–osteoblast interactions." (PMID 27600237, 2015).
renal failure (2 papers, 2015 to 2022). "Indeed, there is no clear evidence on the mechanism of action of ADAMTS-4 in renal failure although its function may be assumed by studying its role in other organ systems." (PMID 35328201, 2022).
thoracic aortic aneurysm (2 papers, 2020 to 2025). An aneurysm formed in the wall of the proximal portion of the descending aorta proceeding from the arch of the aorta. "The proteolysis of versican by ADAMTS4 also contributes to fetal membrane rupture at parturition, as well as the development of thoracic aortic aneurysms and dissections." (PMID 40002887, 2025). "ADAMTS4 protein and mRNA are expressed at higher levels in thoracic aortic aneurysm and dissection tissues than in control aortic tissues, and increased ADAMTS4 levels can degrade versican and facilitate macrophage invasion." (PMID 32095376, 2020).